PIGC (phosphatidylinositol glycan anchor biosynthesis class C)
Description:
Part of the glycosylphosphatidylinositol-N-acetylglucosaminyltransferase (GPI-GnT) complex that catalyzes the transfer of N-acetylglucosamine from UDP-N-acetylglucosamine to phosphatidylinositol and participates in the first step of GPI biosynthesis.
Synonyms: PIG-C; GPI2; GPIBD16; MRT62
Tractability: Antibody: UniProt predicts a signal peptide or a membrane-spanning region. PROTAC: ubiquitination databases record sites on it.
Gene: Protein-coding gene on chromosome 1 (172,370,189 to 172,444,148, reverse strand). Ensembl gene ENSG00000135845.
Subcellular location: Endoplasmic reticulum membrane
Pathways (Reactome):
Metabolism of proteins: Synthesis of glycosylphosphatidylinositol (GPI)
Gene Ontology:
Molecular function: protein binding; catalytic activity
Biological process: GPI anchor biosynthetic process
Cellular component: endoplasmic reticulum membrane; glycosylphosphatidylinositol-N-acetylglucosaminyltransferase (GPI-GnT) complex; membrane
Genetic constraint (gnomAD): Loss-of-function variants: 14 observed, 21.98 expected, observed/expected ratio (o/e) 0.64, 90% interval 0.42 to 1. The upper end of that interval is the gene's LOEUF score, 1, which puts it in group 4 of 6, group 1 being the genes least tolerant of losing a copy. Missense variants: 310 observed, 371.85 expected, observed/expected ratio (o/e) 0.83, 90% interval 0.76 to 0.92. Synonymous variants: 129 observed, 146.13 expected, observed/expected ratio (o/e) 0.88, 90% interval 0.76 to 1.02.
Gene-disease validity (ClinGen):
ClinGen rates the evidence that PIGC causes each of these diseases.
glycosylphosphatidylinositol biosynthesis defect 16 (autosomal recessive): Limited.
Homologues: Orthologues: chimpanzee PIGC (99% identical), macaque PIGC (98% identical), guinea pig PIGC (96% identical), pig PIGC (96% identical), dog PIGC (96% identical), mouse Pigc (94% identical), rat Pigc (93% identical), tropical clawed frog pigc (76% identical), zebrafish pigc (53% identical), Drosophila melanogaster PIG-C (36% identical), Caenorhabditis elegans pigc-1 (29% identical).
Diseases named in the same sentence as PIGC in open-access papers:
PIGC is named in the same sentence as 22 diseases in open-access papers, as found by Europe PMC text mining. Sharing a sentence is not in itself a finding about the gene and the disease. The quoted sentences say what the papers report.
hepatocellular carcinoma (5 papers, 2022 to 2025). A malignant tumor that arises from hepatocytes. "This phenomenon has been highlighted in other cancer contexts, such as hepatocellular carcinoma, where aberrant PIGC expression is linked to poor prognosis through immune modulation and immune cell infiltration." (PMID 39860532, 2025). "Additionally, excessive phosphatidylinositol glycan C (PIGC) gene expression contributes to hepatocellular carcinoma lethality, while a mutation in the PIGC gene is correlated with epilepsy and seizure disorders." (PMID 40102990, 2025). "PIGC enhances hepatocellular carcinoma cell proliferation and migration by modulating the cell cycle, with its overexpression linked to reduced survival rates in liver cancer patient." (PMID 40963867, 2025). "In the study, we attempted to clarify the correlations of PIGC to prognosis and tumor-infiltrating lymphocytes in hepatocellular carcinoma (HCC)." (PMID 36061167, 2022). "Correlation of PIGC mRNA expression and prognosis in hepatocellular carcinoma with different clinicopathological factors by Kaplan-Meier plotter." (PMID 36061167, 2022).
colorectal cancer (2 papers, 2016 to 2022). A primary or metastatic malignant neoplasm that affects the colon or rectum. "The findings in this report shed light on the important role of PIGC in colorectal cancer with HCC and highlights the potential relationship and an underlying mechanism between PIGC and tumor-immune interactions." (PMID 36061167, 2022). "Other candidates, PARG and TDGF1, have been associated with cancer regulation; however, the functional role of the candidates HORMAD1, PIGC, NCAM2, INO80D, SLCO2A1, SLC12A1, and METTL19 was unclear in colorectal cancer." (PMID 27383761, 2016).
epilepsy (2 papers, 2021 to 2025). A brain disorder characterized by episodes of abnormally increased neuronal discharge resulting in transient episodes of sensory or motor neurological dysfunction, or psychic dysfunction. "They concluded that mutations in the PIGC gene were associated with epilepsy and intellectual disability." (PMID 34194475, 2021).
liver cancer (2 papers, 2022 to 2025). An epithelial or non-epithelial malignant neoplasm that arises from the liver. "In our study, we found that the expression levels of PIGC are upregulated in brain and CNS, cervical, esophageal, head and neck, and liver cancer, along with myeloma and sarcoma." (PMID 36061167, 2022). "Furthermore, the highest expression levels of PIGC was greatest in liver cancer according to Oncomine, GEPIA and TIMER analyses." (PMID 36061167, 2022).
bladder cancer (1 paper, 2019). "Two proteins of the glycosylphosphatidylinositol (GPI) anchoring system, PIGU and PIGC, were top genes with respect to significant monotonic expression; of these, PIGU is a known bladder cancer oncogene." (PMID 31277598, 2019).
breast carcinoma (1 paper, 2017). "Upon inhibition of miR-7641 expression, the expressions of several of the target genes (RPS16, RNF4, EMC8, and MSRB3) increased, CUL3 expression decreased, and other genes, including PIGC, remained unchanged in MCF-7 breast cancer cells." (PMID 28827731, 2017). "Similarly, miR-7641 inhibition in MDA-MB-231 breast cancer cells upregulated RPS16, TNFSF10, MSRB3, CDNF, ZNF616, and NBEA, downregulated CUL3, and showed no remarkable changes for PIGC and the other genes." (PMID 28827731, 2017).
Macrocephaly (1 paper, 2024). Occipitofrontal (head) circumference greater than 97th centile compared to appropriate, age matched, sex-matched normal standards. "Interestingly, macrocephaly has been reported in patients with mutations in PIGA, PIGC, and PIGM, which are involved in the initial stages of GPI anchor biosynthesis." (PMID 40225942, 2024).
Obesity (1 paper, 2020). Accumulation of substantial excess body fat. "PIGC, which exhibits fat depot-specific mRNA expression, is known to associate with lipid metabolism and obesity." (PMID 32580275, 2020).
pancreatic ductal adenocarcinoma (1 paper, 2025). An infiltrating adenocarcinoma that arises from the epithelial cells of the pancreas. "A study found mutations in PIGC in the pancreatic ductal adenocarcinoma cell line AsPC-1, and these mutations enhanced the motility of cancer cell." (PMID 40963867, 2025).
pneumonia (1 paper, 2013). An acute, acute and chronic, or chronic inflammation focally or diffusely affecting the lung parenchyma, caused by an infection in one or both of the lungs (by bacteria, viruses, fungi, or mycoplasma.). "Active TB cases were separated from all other groups (i.e. LTBI, HC and non-TB pneumonia) based on expression of PIGC (p = 0.045), GLDC (p = 0.044) and HBD (p = 0.025)." (PMID 23375113, 2013).
virus infection (1 paper, 2025). "The successful knockout of PIGC and PIGH was confirmed by impaired Echo7 virus infection and sequencing of the targeted genomic loci." (PMID 41252368, 2025).
cancer (7 papers, 2016 to 2025). A tumor composed of atypical neoplastic, often pleomorphic cells that invade other tissues. "PIGC catalyses biosynthesis of glycosylphosphatidylinositol and its dysregulation was implicated in the pathogenesis of several malignant tumour types." (PMID 35854233, 2022). "To better understand the relevance and underlying mechanisms of PIGC expression in cancer, we investigated the specific relationship between PIGC expression and the clinical characteristics of HCC patients in KM plotter databases." (PMID 36061167, 2022). "PIGC is over-expressed in breast cancer according to the Human Protein Atlas and cancer genomics databases." (PMID 36061167, 2022). "The expression levels of PIGC mRNA were also higher in all individual cancer stages, but particularly in stage 3." (PMID 36061167, 2022). "Elevated expression of Phosphatidylinositol glycan anchor biosynthesis class C (PIGC) was shown to promote proliferation and cancer cell migration." (PMID 35854233, 2022). "We selected cancer types in which PIGC expression levels had a significant positive correlation with tumor purity in TIMER and a significant correlation with prognosis in GEPIA." (PMID 36061167, 2022). "In this present study, we comprehensively analyzed the expression of PIGC and correlated this data with the prognosis of cancer patients in databases such as Oncomine, Gene Expression Profiling Interactive Analysis (GEPIA), UALCAN and Kaplan-Meier plotter (KM plotter)." (PMID 36061167, 2022). "The correlations between PIGC and cancer immune infiltrates were investigated via TIMER." (PMID 36061167, 2022). "Relatively low levels of PIGC in HCC and other cancer tissues may indicate a greater risk of tumor relapse after treatment and careful medical supervision will be necessary for such patients." (PMID 36061167, 2022). "Additional findings showed that PIGC expression was significantly elevated in HCC patients irrespective of sample type, gender, age, race, cancer stage and tumor grade." (PMID 36061167, 2022).
tumor (2 papers, 2022). "We also investigated the correlation between PIGC and tumor-infiltrating immune cells in different tumor microenvironments via the Tumor Immune Estimation Resource (TIMER)." (PMID 36061167, 2022). "In terms of tumor grading, the expression of PIGC was significantly up-regulated in all tumor grades, particularly grade 3." (PMID 36061167, 2022). "Analysis of the GEPIA databases showed that PIGC expression in HCC tissues were significantly correlated with the expression of marker genes from tumor infiltrating M1 macrophages, Th2 cells, Tfh cells, and Treg cells." (PMID 36061167, 2022). "In summary, our results suggest that PIGC is a potential independent prognostic biomarker for HCC that can be used to evaluate the levels of immune cell infiltration in tumor tissues." (PMID 36061167, 2022). "Then, we investigated the correlation between PIGC expression levels and the status of tumor-infiltrating immune cells based on the gene expression levels of immune marker genes in HCC using the TIMER and GEPIA databases." (PMID 36061167, 2022). "This suggests that PIGC plays an important role in regulating tumor immunity, and therefore could influence the prognosis of HCC." (PMID 36061167, 2022). "Secondly, we did not conduct in vitro or animal experiments to confirm the role of PIGC in the growth and progression of HCC and its relationship with the infiltration of immune cells into the tumor microenvironment." (PMID 36061167, 2022). "Of the remaining 41 genes, three (PIGC, PKM and PPIB) were commonly upregulated with oncogenic potential and 31 were commonly downregulated among CP and PDAC-CP, of which, 3 (AZGP1, EGLN1 and GNMT) were tumour suppressors." (PMID 35854233, 2022). "Similarly, HCC patients with high PIGC levels had higher TIDE scores, indicating that tumor patients might low respond to immunotherapy." (PMID 36061167, 2022).
infection (1 paper, 2023). The state of being infected such as from the introduction of a foreign agent such as serum, vaccine, antigenic substance or organism. "The FAM168B, RAF1, HESX1, USP8, C2CD5, PIGC, ENSGALG00000053041, and ENSGALT00000092369 were found to be top driver genes shared among dpi, body weight post-infection, and propionate and valerate cecal contents." (PMID 36902251, 2023).
PIGC also shares sentences with these, for which no sentence is quoted: genetic diseases (2 papers); abdominal aortic aneurysm (1); asthma (1); central obesity (1); Intellectual disability (1); myeloma (1); Salmonella Infections (1); sarcoma (1).